CD4 (CD4 molecule)
Diseases named in the same sentence as CD4 in open-access papers (continued):
Sharing a sentence is not in itself a finding about the gene and the disease.
psoriasis (continued). "In contrast, CD4+CD25− T cells with CD4+CD25+ T cells were not suppressed in psoriasis patients and underwent cell division 3 to 5 times, like the ratio of CD4+CD25− T cells without CD4+CD25+T cells." (PMID 23365685, 2013). "Interestingly, the frequency of CD57+CD4+ and CD57+CD8+ T cells was significantly higher in unaffected skin of psoriasis patients compared to lesional skin." (PMID 23468834, 2013). "Although Th17 cells, which are classically defined as CD4+ IL-17-producing cells, previously has received the major focus, it has recently been established that also CD8+ IL-17-producing cells contribute to inflammatory skin disorders including psoriasis." (PMID 23094018, 2012). "With regard to the well-known prominent role of IFN-γ in the etiology of this disease, we unexpectedly observed no increased frequencies of IFN-γ producing CD4 or CD8 T cells in the dermis of psoriasis patients compared to healthy skin donors." (PMID 21124836, 2010). "This indicates that the cytokine level secreted by naïve CD4+ T cells is not sufficient to activate a psoriasis-like phenotype and reflects the in vivo situation in which dermal cell and skin-resident T cells also co-exist in an inactivated status without inflammatory response." (PMID 40678130, 2025). "As CD4+ lymphocytes are central to both HIV pathogenesis and psoriasis immunology, the virus's powerful impact on these cells may overshadow the usual effects of latitude (such as variations in UV exposure and vitamin D levels, which modulate psoriasis pathogenesis)." (PMID 41207052, 2025). "Autoimmune attacks may engage, as dominant effectors, CD8+ T cells (e.g. T1D, vitiligo, AA), CD4+ T cells (e.g. MS, SLE, RA, IBD, EAE, autoimmune thyroid diseases, psoriasis), NK cells (e.g. AA, SLE, RA, MS, psoriasis, T1D) or autoantibodies (e.g. SLE, T1D, psoriasis, Grave’s disease, IBD, MS)." (PMID 41383600, 2025). "We therefore, investigate CD4+ and CD8+ T cell memory phenotype, the expression of chemokine receptors and adhesion molecules, as well as markers of activation and T cell exhaustion in splenocytes from mice with recurrent psoriasis-like inflammation and in control mice." (PMID 40599782, 2025). "Moreover, the effect of immunosuppression-induced reduction of CD4 cells on the incidence of psoriasis in other diseases has not been explored." (PMID 41207052, 2025). "In patients with psoriasis who were treated with biologic drugs, the levels of CD3/CD69-, CD4/CD69- and CD19/CD69-positive PBMCs, and CD3/CD69 within CD3+ cells, CD4/CD69 within CD4+ cells, CD4/CD25 within CD4+ cells and CD19/CD69 within CD19+ cells were significantly higher than before therapy." (PMID 37892710, 2023). "The expression level of AIM2 gene in CD4+ tissue-resident memory T (CD4+ Trm) cells was measured in the patients with acute cutaneous lupus erythematosus (ACLE), subacute CLE (SCLE), localized discoid lupus erythematosus (localized DLE), psoriasis, and other inflammatory skin diseases." (PMID 36118867, 2022). "In addition, evidence suggests that an absence of pVHL not only affects the function of CD4 T cells, but also other T cell populations that play a relevant role in psoriasis." (PMID 35563616, 2022). "Moreover, HIV infection is characterized by an increased CD8+ T-cell number with an inverted CD4+/CD8+ ratio suggestive of a chronic inflammatory status, which could lead to the onset of psoriasis." (PMID 35203438, 2022). "Consequently, we showed that the skin of IMQ-induced mice mimics the psoriatic characteristics with increased infiltration of inflammatory cells and increased levels of psoriasis-related cytokines and chemokines such as CXCL1, IL-25, IL-17A, IL-6, IL-1β, IL-36, CD4, and IFN-γ." (PMID 34641629, 2021). "The presence of IL-17 expression in the skin but not on CD4/CD25 blood cells may indicate local rather than systemic involvement in the inflammation process in psoriasis." (PMID 34945130, 2021).
psoriasis (continued). "By targeting Bcl-3, both CD4+ and CD8+ TRM disease pathways in psoriasis could be interrupted." (PMID 34012438, 2021). "The central mechanisms behind psoriasis pathogenesis involve the crosstalk between IIS and AIS and chronic interactions between these and resident skin cells, mainly hyper-proliferative, dysfunctional KCs and infiltrating activated immune cells, largely composed of CD4+ and CD8+ T cells." (PMID 32224981, 2020). "Interestingly, CD8+ T cells infiltrating HS skin did not make appreciable amounts of IL-17A, whereas CD4+ Tcons in lesional HS skin produced similar levels of this cytokine to that of psoriasis." (PMID 32841223, 2020). "This study utilized biochemical, cellular, pharmacological, and tissue engineering tools to characterize the effects of fisetin on normal human epidermal keratinocytes (NHEKs), peripheral blood mononuclear cells (PBMC), and CD4+ T lymphocytes in 2D and 3D psoriasis-like disease models." (PMID 31540162, 2019). "Additionally, CD103+ CD8+ T cells and CCR6+ CD4+ T cells were enriched in non-lesional skin of psoriasis patients compared with that in healthy controls." (PMID 31673756, 2019). "GM-CSF+ CD4 frequency was not affected by co-existent psoriasis or IBD." (PMID 29142230, 2017). "Also, IL-35 may regulate the production of proinflammatory CD4+ T cell cytokines and may decrease local lymphocytic infiltration of Th17 cells in K14-VEGF-A-Tg mice and in mouse models of imiquimod-induced psoriasis." (PMID 29249871, 2017). "Furthermore, the IL-16 mRNA levels within psoriatic lesions positively correlated with the levels of CD4 mRNA, but not with Psoriasis Area and Severity Index." (PMID 27788245, 2016). "In addition, ELISPOT assays using cells from individuals with psoriasis showed that IL-9 had no ex vivo effects on numbers of IFN- γ secreting CD4+ T cells, suggesting that IL-9 makes no contribution on the Th1 component of the disease." (PMID 23335955, 2013). "Foxp3+Treg in peripheral blood mononuclear cells (PBMCs) tended to be lower in psoriasis patients (Treg/CD4; 4.57±2.40%) than in healthy volunteers (Treg/CD4; 6.00±1.39%) before bath-PUVA therapy, but increased significantly after bath-PUVA therapy in all patients (Treg/CD4; 6.40±2.85%)." (PMID 23365685, 2013). "As our main goal was to evaluate the effects of the interaction between sleep deprivation and early stages of psoriasis on cytokines levels, we chose the HNE model due to concerns that possible cytokine changes could be masked in the CD4+/CD45RBhi model due to high baseline cytokine levels." (PMID 23226485, 2012). "This CD4 T cell subset may be similar to that recently reported to secrete IL-22 but not IL-17 and to be involved in the skin pathophysiology of psoriasis." (PMID 20929536, 2010). "Our findings that the knockdown of TAp63 in CD4+ T cells reduces the severity of SKG cell-transfer models of arthritis raises the possibility that an imbalance of TAp63 and ΔNp63 could be involved in the pathogenesis of psoriatic arthritis, which occurs frequently in patients with psoriasis." (PMID 37212280, 2023). "However, treatment with TET NE could not inhibit the proportion of IL-17A-producing CD4- cells in IMQ-induced psoriasis mice." (PMID 35464441, 2022). "Additionally, we found that CD8αα+T cells from patients with psoriasis did not express the markers of regulatory T cells and could promote the proliferation of CD4+T effector cells and produce interleukin‐17 and interferon‐γ." (PMID 35663772, 2021). "Few studies have demonstrated that CD4+ TCM cells are significantly increased in patients with psoriasis 10 while circulating CLA+CCR4+CD8+ TCM cells are also expanded in the patients 11, indicating that TCM cells may be involved in the pathogenesis of psoriasis." (PMID 32929360, 2020).
psoriasis (continued). "Both the CD4+ and CD8+ T cell populations demonstrated attraction to CD2+MHC-II+CCR2+ myeloid precursors in the noninflamed synovia of individuals with psoriasis and the inflamed synovia of individuals with PsA." (PMID 41482544, 2026). "For example, methotrexate, a well‐known drug for the treatment of psoriasis, does not seem to alter HIV replication but leads to a reduction in CD4 levels." (PMID 40176606, 2025). "In conclusion, we show that T-helper cells, cytotoxic T cells and B cells from a subgroup of patients with psoriasis respond to challenge with citLL37, but not native LL37, with production of IFN-γ accompanied by production of IL-10 by CD4+ T cells." (PMID 38173716, 2023). "Unlike other inflammatory diseases where CD4+ Th17 cells are the main IL-17 producing T-cell subset, CD8+ T-cells are also an important source of IL-17 in psoriasis skin (Tc17 cells)." (PMID 36110854, 2022). "“Treat all” where all patients are treated with antiretroviral therapy (ART) regardless of CD4 cell counts was started in 2017 at the HIV Clinic and all 31 patients diagnosed with psoriasis attending the MRFTT who were alive during the study were on ART." (PMID 35225942, 2022). "This CD4+ T cell-driven process proceeds to CD8+ T cell recruitment and activation, as the development of psoriasis in animal models is eliminated by inhibiting CD8+, but not CD4+, T cells." (PMID 34371756, 2021). "In psoriasis animal models, the injection of CD4+, but not CD8+, T cells from psoriatic patients induced psoriasis in SCID mice." (PMID 34371756, 2021). "Since we found that DHA attenuated the recurrence of psoriasis and diminished CD8+, but not CD4+, TCM pool, it's possible that CD8+ TCM cells play a more important role in psoriasis relapse than do CD4+ TCM cells." (PMID 32929360, 2020). "Administration of recombinant IL-15 or CD8+, but not CD4+, TCM cells resulted in complete recurrence of psoriasis in mice previously treated with DHA." (PMID 32929360, 2020). "The issue of the expression of negative costimulatory molecule PD-1 on the peripheral CD4+ and CD8+ T cells was interesting enough for us to launch an innovative research into its role in the psoriasis pathogenesis." (PMID 29180838, 2017). "In psoriasis samples, AQP9 exhibited significant negative correlations with T cells CD4 memory activated, T cells CD4 memory resting, Macrophages M1, and dendritic cells activated, while it showed significant positive correlations with mast cells resting, plasma cells, and B cells memory." (PMID 40093802, 2025). "Further analyses on the function of DCs and CD4+ T cells revealed no significant alterations in PBMC and iLN, suggesting that the topical application of TYK2 inhibitor did not significantly affect the global immunity of psoriasis mice." (PMID 40038877, 2025). "Furthermore, depletion of γδ T cells, but not depletion of CD4-positive T cells including Th17 cells, suppressed symptoms of IMQ-induced psoriasis in mPGES-1−/− mice." (PMID 40481552, 2025). "Notably, we observed a negative correlation between miR-125a-5p expression in CD4+ T cells and the PASI scores of psoriasis patients." (PMID 37773129, 2023). "We found that the proportion of CaMK4+ cells and the mean fluorescence intensity (MFI) of CaMK4 were both higher in peripheral T cell subsets (CD4+, CD8+, and double-negative (DN) cells) and CD14+ monocytes from patients with psoriasis than in those from healthy controls." (PMID 35869084, 2022). "Indeed, adoptive transfer of CD8+, but not CD4+, TCM cells to DHA-treated psoriatic mice reversed the therapeutic effects of DHA on psoriasis relapse." (PMID 32929360, 2020). "The injection of CD4+, and not CD8+, T cells obtained from psoriatic patients into human non-lesional skin in vitro, and then grafted onto immunodeficient mice model (SCID mice), has been shown to be responsible for psoriasis development." (PMID 29316717, 2018).
psoriasis (continued). "Conversely to the CD4+ T cell-based psoriasis model, an early epidermal infiltration of CD8+ T cells is thought to be essential for the onset of psoriasis inflammation, rather than the dermal infiltration of CD4+ T cells." (PMID 29316717, 2018). "Most notably, CLE and DM lesions were enriched for Th1-skewed CD4+ T cells that, unlike their counterparts in vitiligo, expressed cytotoxic effector molecules including GZMB, GZMK, and PRF1, a population nearly absent in healthy and psoriasis skin (scCODA FDR < 0.1)." (PMID 40894544, 2025). "Previous studies have shown that activated CD4 T cells, rather than CD8 T cells, are considered the main source of IL-17 in the blood Significantly decreased Th17 cells and IL-17 expression were also found in peripheral blood and skin of psoriasis patients treated with topical therapy." (PMID 40391222, 2025). "The psoriasis treatment guideline of the American Academy of Dermatology mentions that IBs (anti-TNF, anti-IL12/23, anti-IL17 and anti-IL23) can be used in patients with HIV infection, provided they are receiving ART, have normal CD4, undetectable viral load and do not have recent OIs." (PMID 38238209, 2024). "Neither native nor citLL37 induced IFN-γ-producing CD4+ T cells in MNC cultures from HDs, while citLL37 induced a significant increase in the proportion of IFN-γ-producing CD4+ and CD8+ T cells in cultures from patients with psoriasis compared to unstimulated- and native LL37-stimulated cultures." (PMID 38173716, 2023).
multiple sclerosis (435 papers, 2006 to 2026). A progressive autoimmune disorder affecting the central nervous system resulting in demyelination. "Recently, it was shown that MCAM is at the center of a pathological pathway used by brain endothelial cells to recruit pathogenic CD4 + T lymphocytes from the circulation early during neuroinflammation in multiple sclerosis." (PMID 41388158, 2025). "Collectively, these results highlight the potential of Lycium barbarum glycopeptide as an innovative therapeutic agent for CD4 + T cell-associated autoimmune or inflammatory diseases, such as multiple sclerosis." (PMID 40145961, 2025). "Multiple sclerosis and some other neuroinflammatory diseases are associated with aberrant CD4+ T cell differentiation and regulatory T cell function." (PMID 39013878, 2024). "Several variants in the LAG3 and CD4 genes have been associated with the risk for multiple sclerosis (rs1922452 A > G) and Parkinson’s disease." (PMID 39769168, 2024). "In CD4+ T cells of controls, vitamin D level was associated with expression levels of several genes proximal to multiple sclerosis risk loci (P = 0.01)." (PMID 38228657, 2024). "The most statistically significant association with disease was observed for factor 9 in CD4+ T cells (P = 0.007; permutation test at the donor level), where patients with multiple sclerosis had reduced expression compared to IIH." (PMID 38038362, 2024). "have shown that CD56brightCD16lowNK cells subset was able to inhibit autologous CD4+T cell proliferation, which was associated with multiple sclerosis course." (PMID 37124743, 2023). "For instance, multiple sclerosis is confirmed to be an autoimmune inflammatory disease caused by the recruitment of self-reactive lymphocytes (mainly CD4+ T cells) in the central nervous system." (PMID 37900961, 2023). "Multiple sclerosis is thought to be caused by the activation of peripheral autoreactive CD4+ T cells." (PMID 36768494, 2023). "CD4+ T lymphocytes are implicated in the pathogenesis of multiple sclerosis by a strong association of disease susceptibility with MHC class II alleles, but the mechanism is largely unclear." (PMID 36113749, 2022). "It is associated with increased disease activity in multiple sclerosis together with an increase in CCR6+CD4+ T cells with migratory properties." (PMID 35378908, 2022). "HLAclass II is the major multiple sclerosis genetic risk locus and is expressed onactivated CD4+ T-cells." (PMID 34761221, 2021). "Here the authors map cis and trans methylation QTL in CD4 + T cells from patients and colocalize with GWAS loci in order to interpret genetic variants associated with multiple sclerosis." (PMID 34873174, 2021). "For example, Th1 CD4 T cells promote cell-mediated immunity and in autoantigenic cases have been heavily implicated in the inflammatory CNS disease multiple sclerosis." (PMID 31993745, 2020). "Activated CD4+ T cells can cause neuronal damage directly as seen in multiple sclerosis or by activating other immune cell types, such as microglia, through secreted cytokines such as IFN-γ." (PMID 30097565, 2018). "Such infiltration of CD4+ T cells causes CNS autoimmune diseases such as multiple sclerosis (MS) and experimental autoimmune encephalomyelitis (EAE)." (PMID 29238350, 2017). "Both serological and CD4 T cell responses directed against EBNA-1 have been associated with multiple sclerosis, with further evidence that EBNA-1-specific antibodies differentiate disease-discordant identical twins." (PMID 26849221, 2016). "We also show inverse correlation between THEMIS expression in human CD4+ T-cells and dosage of the multiple sclerosis risk allele at rs13204742, driven by reduced expression of exon 1- containing isoforms." (PMID 27438997, 2016). "Here the authors show that it also plays a critical role in pathogenic CD4+ cells in a mouse model of multiple sclerosis, and its inactivation ameliorates the chronic stage of the disease." (PMID 26436530, 2015).